ITGA4 (integrin subunit alpha 4)
Diseases named in the same sentence as ITGA4 in open-access papers (continued):
Sharing a sentence is not in itself a finding about the gene and the disease.
tumor (continued). "When GISTs with negative, low or high ITGA4 expression were compared, ITGA4 expression was associated with a tumour location in the stomach, the high NIH risk stratification group for recurrence, presence of tumour necrosis, and a high tumour mitotic count (all P‐values <0.05)." (PMID 29377440, 2018). "Therefore, ITGA4 may influence the TME by modulating immune cell infiltration and function in various cancers, where these immune cells have complex roles in promoting or inhibiting tumors, highlighting ITGA4’s potential as a therapeutic target of controlling tumor immune suppression." (PMID 40012546, 2025). "Moreover, ITGA4 showed a consistent negative correlation with RNAss in most cancers, and its relationship with other stemness scores (EREG.EXPss, DNAss, DMPss, ENHss, EREG-METHss) varied in direction and degree, potentially affecting tumor cell drug resistance." (PMID 40012546, 2025).
cancer (56 papers, 2007 to 2025). A tumor composed of atypical neoplastic, often pleomorphic cells that invade other tissues. "Genetic alterations of ITGA4, primarily somatic missense mutations, were identified in 22 of 30 cancer types, potentially giving tumors a growth advantage by causing abnormal protein functions." (PMID 40012546, 2025). "We focused on the immune cell infiltration associated with ITGA4 expression in the overall cancer context." (PMID 40012546, 2025). "Prognostic analysis demonstrated that its expression levels correlated with OS, DSS, PFI, and DFI in various cancers, acting as a risk or protective factor, emphasizing the complex role of ITGA4 in cancer prognosis." (PMID 40012546, 2025). "ITGA4 mediates cell–cell adhesions and is linked to cancer progression, inflammatory reactions, and ECM stemness." (PMID 39723668, 2025). "So, ITGA4 methylation is associated with cancer development and progression and has potential as a biomarker for early cancer screening." (PMID 40012546, 2025). "Furthermore, regulatory T cells (Tregs), cancer-associated fibroblasts (CAFs), and endothelial cells, also demonstrated significant positive correlations with ITGA4 in multiple cancers." (PMID 40012546, 2025). "ITGA4 demonstrated diagnostic potential in 20 cancer types (AUC>0.7)." (PMID 40012546, 2025). "Furthermore, the expression levels of cell proliferation and cytoskeleton-related proteins increased consistently during cancer development, such as ITGA4, DDC, and CPT1A; thus, they are potential diagnostic markers." (PMID 35958927, 2022). "Additionally, ITGA4 showed good diagnostic potential in 20 cancer types." (PMID 40012546, 2025). "Interestingly, Vcam1, Sele, and Pdpn could potentially associate with genes found in the cancer cell transcriptome, such as Itga4 and Lgal3bp." (PMID 37686421, 2023). "Further analysis revealed that ITGA4 was significantly negatively correlated with MSI in seven cancer types and with TMB in ten types." (PMID 40012546, 2025). "Integrin α4 (ITGA4) has been implicated in various disorders, including gastrointestinal diseases, cancer, among others, though specific research on ITGA4 in LF remains sparse." (PMID 40103586, 2025). "The flow cytometry analysis showed that knockdown of ITGA4 or ITGB1 can inhibit the effect of recombinant SPP1 protein or cancer cells on M2 TAM polarization (Additional file4N)." (PMID 40665335, 2025). "Among the 18 ITGA4 methylation sites analyzed, except for cg05246303 and cg25515269, the remaining 16 sites showed significant variations in over ten types of cancer." (PMID 40012546, 2025). "We subsequently evaluated the predictive efficacy of ITGA4 for immunotherapy outcomes in cancer patient cohorts treated with ICB." (PMID 40012546, 2025). "The flow cytometry analysis showed that knockdown of ITGA4 or ITGB1 can inhibit the effect of recombinant SPP1 protein or cancer cells on the function of CD8+T cells (Additional file3N)." (PMID 40665335, 2025). "We then analyzed ITGA4 mRNA levels using the TCGA database, observing significant expression differences in most cancer types (18 of 24)." (PMID 40012546, 2025). "To validate the pan-cancer findings of ITGA4, we investigated its role in GC using the TCGA-STAD cohort." (PMID 40012546, 2025). "ITGA4 is a potential biomarker and therapeutic target to enhance cancer treatment and improve patient outcomes." (PMID 40012546, 2025). "Subsequently, using univariate Cox regression forest plots and KM survival curves, we assessed the prognostic implications of ITGA4 expression across different cancers." (PMID 40012546, 2025). "The intersection of these datasets revealed nine hub genes, with a pan-cancer heatmap confirming their positive correlation with ITGA4." (PMID 40012546, 2025).
cancer (continued). "We then conducted a detailed analysis using five distinct algorithms to elucidate the relationship between ITGA4 expression and immune cell infiltration across various cancer types." (PMID 40012546, 2025). "We observed a poorer prognosis in patients with top 20% ITGA4 expression compared to those with the bottom 20%, correlating with findings from pan-cancer studies linking higher ITGA4 expression to advanced GC stages and grades." (PMID 40012546, 2025). "In contrast to normal tissues, ITGA4 expression significantly differed across various cancer types and different molecular and immune subtypes, suggesting its functional diversity throughout cancers." (PMID 40012546, 2025). "To explore the mechanism and clinical significance of ITGA4 in cancer, we conducted a series of subsequent analyses." (PMID 40012546, 2025). "We further found that ITGA4 was positively correlated with most immune regulatory molecules across cancers, such as CTLA4, PDCD1, LAG3, which inhibit T cell activity." (PMID 40012546, 2025). "Further studies are required to elucidate more molecular mechanisms of ITGA4 to advance cancer diagnosis and treatment." (PMID 40012546, 2025). "This study systematically analyzed the role of ITGA4 in pan-cancer and validated some of its functions through experiments." (PMID 40012546, 2025). "There were strong connections via the GAS6-AXL/MERTK and THBS1-CD36/CD47/ITGA4/ITGB1/LRP1 axes between cancer cells (contributing ligands) and TAMs (contributing receptors)." (PMID 38169544, 2024). "We found that the high expression of ITGA4 affects the immune infiltration status of cancer tissues, especially related to the enrichment of macrophages." (PMID 36254221, 2022). "Overexpression of integrin α4 (ITGA4) has been reported in several cancers which mediates migration of cancerous cells." (PMID 33816236, 2021). "In this study, we report that ITGA4 is often expressed strongly in GISTs compared to many other cancers and histopathologically normal human tissues, suggesting a molecular pathologic role for ITGA4 in GIST." (PMID 29377440, 2018). "ITGA4 mRNA expression was high in GISTs as compared with other types of cancer and healthy gastrointestinal tract tissues available in the MediSapiens database (IST OnlineTM at ist.medisapiens.com) based on the GTI outlier analysis." (PMID 29377440, 2018). "Additionally, ITGA4 regulated multiple canonical cancer signaling pathways, such as PI3K-AKT, RAS-MAPK, RTK, and TSC-mTOR pathways." (PMID 40012546, 2025). "Therefore, ITGA4 and its mediated signaling pathways play critical roles in the growth, invasion, migration, and immune evasion of malignant tumors." (PMID 40012546, 2025). "Moreover, ITGA4 impacts several classic cancer-related signaling pathways including PI3K-Akt, JAK-STAT, NF-kappa B, and Toll-like receptor pathways." (PMID 40012546, 2025). "Concurrently, ITGA4 expression varied across different immune subtypes in 23 cancer types." (PMID 40012546, 2025). "Data from the CancerSEA database showed at the single-cell level that ITGA4 may impact cellular quiescence, differentiation, apoptosis, and processes related to cancer metastasis, invasion, and angiogenesis." (PMID 40012546, 2025). "Additionally, future research should include deeper cell and animal studies to clarify ITGA4 mechanisms in cancer, along with larger-scale data analyses for cancer types with small sample sizes." (PMID 40012546, 2025). "However, there were some variations in the correlation between ITGA4 expression and immune cell infiltration across different cancer types." (PMID 40012546, 2025). "Furthermore, methylation at cg04531425, cg11947981, cg16057262, cg25024074, cg21995919, cg10965575, cg17265419, cg25515269, and cg05246303 were found to inhibit ITGA4 expression in various cancers." (PMID 40012546, 2025). "Furthermore, we validated ITGA4 in GC only, emphasizing the need for further research across other cancer types." (PMID 40012546, 2025).
cancer (continued). "The Integrin Subunit Alpha 4 (ITGA4) plays important roles in cancers pathogenesis." (PMID 36254221, 2022). "Second, functional characterization and verification of the role of ITGA4 in immune cells will be very important to determine whether the cancer promoting effect of ITGA4 in the GC microenvironment is a driver or a bystander." (PMID 36254221, 2022). "In addition, the analysis of immune cell components in cancer tissues showed that there was more macrophages that were enriched in the tissues with high expression of ITGA4." (PMID 36254221, 2022). "Like any other CpG island, that of the ITGA4 gene may acquire abnormal methylation in the process of cancer progression given general deregulation of epigenetic processes in tumors." (PMID 33500458, 2021). "Opposingly, methylation of the ITGA4 gene that encodes another integrin alpha subunit (α4) is already described as a biomarker for different cancers, but not in PCA." (PMID 34944974, 2021). "Higher-level ITGA4 expression may suppress the detachment and invasion of cancer cells and, on the other hand, may promote their dissemination by increasing their interaction with surface ligands of endothelial cells." (PMID 33500458, 2021). "In addition, the prognostic role of ITGA4 expression in cancer cells was investigated in a series of 147 GIST patients with immunohistochemistry." (PMID 29377440, 2018). "Therefore, ITGA4-targeted drugs combined with immunotherapy may represent an effective cancer treatment strategy." (PMID 40012546, 2025). "Thus, the differential expression of ITGA4 across various cancers may be related to its distinct methylation status in each cancer type." (PMID 40012546, 2025). "In addition, ITGA4 has been shown to be dysregulated in many cancer types and hence may be a potential target for therapy, assuming sufficiently effective splice switching/suppression can be induced." (PMID 31506448, 2019). "Integrin Subunit Alpha 4 (ITGA4), a member of the integrin protein family, is involved in the progression of malignant tumors." (PMID 40012546, 2025). "Our analysis revealed that, among the genes studied, CLEC11A, ICAM4, ITGA4, and AVP exhibited the highest specificity to AML when compared to other cancer types." (PMID 39484036, 2024). "VCAM-1 can tether macrophages to cancer cells via counter-receptor α4β1-integrins, and we found that macrophages and fibroblasts in the SPTCL microenvironment highly expressed ITGA4 and ITGB1, which constitute α4β1-integrins." (PMID 33816243, 2021). "The bisulfite sequencing PCR amplicons of ITGA4 and ZNF549 from non-cancer cell line NP460 and NPC cell line HK1_EBV were also subjected to BGS, and at least five clones were successfully evaluated for all CpG methylation statuses." (PMID 28716111, 2017). "In contrast, METTL3, as a methyltransferase, plays a pro-cancer role in AML by increasing the half-life of ITGA4 mRNA through m6A methylation, thereby elevating ITGA4 protein levels and facilitating chemoresistance through enhanced AML cell homing and engraftment." (PMID 40271153, 2025). "Due to the current lack of systematic understanding of ITGA4, we conducted a comprehensive pan-cancer analysis." (PMID 40012546, 2025). "It has been reported that MDK interacts with the ITGA4 and ITGA6 receptors, activating a series of downstream signaling cascades that significantly enhance cancer cell growth, migration, metastasis, and angiogenesis, thereby further exacerbating the progression of HCC." (PMID 40333631, 2025). "Methylation analysis showed elevated ITGA4 methylation in several cancers, with a negative correlation between methylation and expression in eight cancer types, and a positive correlation in three." (PMID 40012546, 2025). "Overall, except for UCS, ITGA4 expression showed significant correlations with the infiltration of multiple immune cell types, especially macrophages, CD8+ T cells, and CD4+ T cells, in most cancers." (PMID 40012546, 2025).
cancer (continued). "Interestingly, only the cancer progenitor cells highly express cell-to-cell interaction-related genes, for example, ICAM4, MAEA, ITGA4, which are critical in establishing the stem cell niche for erythropoiesis." (PMID 38649187, 2024). "We found the expression of direct interaction partners in cancer cells and LEC, such as Itga4 and Vcam1, which could modulate heterotypic adhesion and maintenance at not only the same niche but also vessel remodeling and immune recruitment." (PMID 37686421, 2023). "ITGA4 and TGFB1 have been found to be co-expressed in four cancer studies." (PMID 37967122, 2023). "ITGA4 and ITGA5 are well-known fibronectin receptors that are altered in many cancer types." (PMID 26056562, 2015). "Specifically, Fluorouracil and t-dcyd exhibit negative correlations with ITGA4 expression levels, with protein docking free energies of -4.53 kcal/mol and -5.47 kcal/mol respectively, indicating that cancers with higher ITGA4 may respond better to these drugs." (PMID 40012546, 2025). "Given that ITGA4 is not expressed in normal breast, one might suggest that its abnormal promoter hypermethylation in cancer is non-functional and is thus merely a passenger epimutation." (PMID 33500458, 2021). "Here, we deepened the study on nine of them (ASS1, EIF4G1, GALNT7, GLUT1, IGF2BP3 (IMP3), ITGA4, RAN, SOD1, and THBS2) to ascertain whether they are truly mesothelial cancer driver genes (CDGs) or genes overexpressed in an adaptive response to the tumoral progression (“passenger genes”)." (PMID 32659970, 2020). "Since the interaction of ITGA4 with VCAM-1 is essential for the leukocyte adhesion cascade involving rolling, adhesion and transmigration through endothelial cells, DcR3 might enable cancer cells to mimicry this process in order to form distant metastasis." (PMID 24107265, 2013).
infection (30 papers, 2010 to 2025). The state of being infected such as from the introduction of a foreign agent such as serum, vaccine, antigenic substance or organism. "“PI3K/AKT” and “Integrin signalling” were significant in IPA of the IA-H/S data set and several infection-associated genes involved in integrin signalling, possess differences in the number of TashAT2 binding motifs between the two genomes (LAMC1, ACTA2, ITGA4 and ITGB5)." (PMID 35061738, 2022). "The genes ITGA4 and TLR3 were related to initial rejection and innate immune response infection of H. contortus in Florida Native sheep." (PMID 39883377, 2025). "B cell transcriptomics indicated significant downregulation of several adhesion molecules during infection, including S1PR1, S1PR2, ITGA4, ITGA6, GPR183, and CCR7." (PMID 37146079, 2023). "Upregulation of ITGA4 and downregulation of SELL in HIV-infected cells in this study are consistent with the idea that at least some of the initial responses to HIV infection may continue to persist into the latency stage long-term after infection." (PMID 37111397, 2023).
heart disease (1 paper, 2017). "Some of those genes, including ITGA4, ITGB8, MYL7, ITGB7, HIF-1α and BNP, are assosiated with heart disease pathways and are recognized as myocardial injury biomarkers." (PMID 28692647, 2017).
metabolic disorder (1 paper, 2020). "The expression of ITGA4, the receptor for the VCAN ligand, was downregulated in C1, a condition favoring the ACAN metabolic disorder found in C1." (PMID 33298863, 2020).
ITGA4 also shares sentences with these, for which no sentence is quoted: Crohn disease (5 papers); Autoimmunity (4); Duchenne muscular dystrophy (4); multiple myeloma (3); pancreatic cancer (3); progressive multifocal leukoencephalopathy (3); rheumatoid arthritis (3); allergies (2); Alzheimer disease (2); autism (2); brain injury (2); brain tumors (2); cardiomyopathy (2); diabetes (2); gastrointestinal stromal tumor (2); influenza (2); lupus- (2); malaria (2); myelodysplastic syndrome (2); neurological disease (2); abscesses (1); acute leukemia (1); acute lymphoblastic leukemia (1); acute promyelocytic leukemia (1); adenocarcinoma (1); allergic asthma (1); allergic dermatitis (1); allergic rhinitis (1); aortic stenosis (1); Arthritis (1).
A further 49 diseases each share a sentence with ITGA4 in 1 paper.